PRL (prolactin)
Diseases named in the same sentence as PRL in open-access papers (continued):
Sharing a sentence is not in itself a finding about the gene and the disease.
adenoma (continued). "The importance of mixed GH and prolactin secreting adenomas in AIP-mutated patients is also highlighted by the experience of one case in the kindred whose profile suggests that mild IGF-1 excess might have developed over time." (PMID 32604740, 2020). "Moreover, the use of exogenous estrogen is associated with hyperplasia of lactotrophs, as well as prolactin-secreting adenomas in menopause females." (PMID 31336780, 2019). "Indeed, higher rates of mixt ACTH- and PRL-secreting adenomas are typically seen in patients harboring the MEN-1 mutation, otherwise they are regarded as a rather rare clinical finding." (PMID 26869991, 2016). "Two patients had a VHL mutation, one with a PRL and one with a GH- and PRL-secreting adenoma." (PMID 25494863, 2015). "Hence, depending on which tumors and cell populations cause prolactin immune-reactivity in dual staining adenomas, clinical features, and remission response may be different in various studies." (PMID 34530798, 2021). "As prolactin usually positively correlates with tumor size, samples in patients with giant adenomas and typical prolactinoma symptoms should be diluted." (PMID 41017446, 2026). "Adenomas were classified according to immunohistochemical staining as GH-only, GH/PRL, or other subtypes." (PMID 42149337, 2026). "PRL-secreting Adenomas: The predominant cognitive deficits include executive function and attention." (PMID 40370784, 2025). "In women, no significant changes in RBC parameters were observed at diagnosis or after PRL normalization, regardless the adenoma size." (PMID 39900728, 2025). "DA therapy remains the cornerstone of prolactinoma treatment in our region and is very effective in normalizing PRL levels, shrinking adenomas, and improving clinical symptoms; DA can be used even in cases of giant prolactinomas." (PMID 41178903, 2025). "Variables that were significantly associated with remission in univariate analysis were included in the model, namely baseline serum PRL, PRL normalization at 6 months, and adenoma diameter." (PMID 41178903, 2025). "Our outcomes regarding adenoma shrinkage and normal prolactin levels with a dopamine agonist regimen were consistent with previous findings in the literature." (PMID 41178903, 2025). "Among them, one case in the CECS group was a PRL-secreting adenoma, while the remaining cases were GH-secreting adenomas." (PMID 39894800, 2025). "Among the secreting adenomas, 26.5% were prolactin-secreting (the most common), 4.1% were GH-secreting, 2% were ACTH-secreting, and 2% were TSH-secreting." (PMID 40227627, 2025). "Dopamine agonists (DA) are the cornerstone treatment for prolactinomas, resulting in the normalization of prolactin (PRL) levels, adenoma shrinkage, and restoration of gonadal function." (PMID 41178903, 2025). "For the first time, we demonstrate that female-specific PRL thresholds for identifying adenoma invasiveness are lower compared to male-specific thresholds and show no significant dependence on age and obesity." (PMID 40113928, 2025). "Both groups showed comparable declines in prolactin levels, and the proportion of patients with reduced adenoma size was similar across all follow-up periods." (PMID 41199869, 2025). "DA remains the cornerstone of prolactinoma treatment in our region, demonstrating high efficacy in normalizing serum PRL levels, reducing adenoma size, and improving clinical symptoms." (PMID 41178903, 2025). "She underwent transsphenoidal surgery at 16 weeks of pregnancy, and pathological examination showed a single adenoma with two different cell components staining for PRL/PIT1 and ACTH/TPIT, respectively." (PMID 41201503, 2025). "Prolactin was markedly elevated (600 ng/mL), suggesting a mixed adenoma, but immunohistochemistry ruled this out." (PMID 40950831, 2025). "A plurihormonal Pit-1-positive adenoma is an adenoma that shows immunohistochemical staining for hormones such as GH, PRL, β-TSH, and/or α-SU." (PMID 40002261, 2025).
adenoma (continued). "Factors favoring remission include older maternal age, lower prolactin levels at diagnosis and postpartum, and smaller adenoma size at diagnosis." (PMID 39816925, 2025). "Other functioning adenomas include somatotrophinomas (24%, secreting growth hormone alone or growth hormone and prolactin, resulting in acromegaly) and adrenocorticotrophinomas (<5%, secreting ACTH, resulting in Cushing disease)." (PMID 40361982, 2025). "They found that DA resulted in adenoma shrinkage in 92.3% of patients and that PRL level was a good predictor of adenoma reduction." (PMID 41178903, 2025). "Our study unveils a notable disparity in PRL thresholds between genders: (i) females exhibit lower thresholds for adenoma invasiveness compared to males, demonstrating consistent performance across various age and obesity categories." (PMID 40113928, 2025). "In our study, plurihormonal Pit-1-positive adenoma tumors mainly secreted PRL, GH, TSH, ACTH, FSH, and LH." (PMID 40002261, 2025). "In this context, this study goes a step further and unveils a notable disparity in PRL thresholds between genders, with females exhibiting lower thresholds for adenoma invasiveness compared to males." (PMID 40113928, 2025). "Prolactinomas are prolactin (PRL) secreting adenomas derived from lactotropic cells in the pituitary gland." (PMID 39949381, 2025). "A positive correlation was also observed between baseline serum prolactin levels and maximum tumor diameter, which was stronger in aggressive adenomas (r = 0.679; p = 0.047)." (PMID 41219436, 2025). "Silent lactotroph adenoma differs from typical prolactin-secreting adenomas in terms of clinical presentation and biochemical profile." (PMID 41140514, 2025). "PRL-PitNETs are treated with surgery or dopamine agonists depending on adenoma size, clinical factors and patient preference." (PMID 40995599, 2025). "The most frequent are prolactin-secreting adenomas (60%), which usually affect young women presenting with galactorrhea and secondary amenorrhea." (PMID 40361982, 2025). "Our treatment approach involved gradually tapering medications after 24 months of initiating medical therapy, provided that PRL levels had normalized or an adenoma reduction of over 50% was achieved." (PMID 39904877, 2025). "This study identified adenoma size and preoperative prolactin level as significant predictors of remission." (PMID 41199869, 2025). "Transsphenoidal pituitary surgery (TSS) is the first-line therapy for all PAs requiring surgical resection, except for prolactin (PRL)-secreting adenomas." (PMID 40370784, 2025). "Baseline PRL <10,638.2 mIU/L (500 ng/mL) and adenoma diameter <10 mm were both independent predictors of remission (P = 0.03 for each)." (PMID 41178903, 2025). "Data from medical records were analyzed to correlate patient demographics, clinical presentation, serum prolactin (PRL) levels, and adenoma size on MRI, both at diagnosis and after initiation of dopamine agonist (DA) therapy, with treatment outcomes." (PMID 41178903, 2025). "In the case of the double adenoma, a CD was confirmed and clearly in the foreground, and laboratory tests also confirmed a significant elevation in PRL levels (> 100-fold)." (PMID 40579705, 2025). "Patients with an adenoma size of less than 40 mm were more likely to have normal PRL after 6 months (P = 0.006)." (PMID 41178903, 2025). "NFPA accounted for the highest frequency (39.2%), followed by GH-secreting adenomas (28.7%), ACTH-secreting adenomas (18.7%), and PRL-secreting adenomas (10.9%)." (PMID 40370784, 2025). "In a prospective study of 71 males with macroadenomas, the likelihood of achieving normoprolactinemia was higher in those with lower prolactin levels and smaller adenomas at presentation." (PMID 40995599, 2025). "Our findings demonstrate significant gender differences in PRL thresholds for adenoma invasiveness, highlighting their potential role in shared decision-making for first-line therapy." (PMID 40113928, 2025).
adenoma (continued). "One year later, a repeat MRI and prolactin level showed a near resolution of the adenoma and a markedly reduced prolactin level." (PMID 39221401, 2024). "Dopamine therapy is used in prolactin-secreting macro-adenomas since it is one of the primary regulators of pituitary prolactin production." (PMID 39006623, 2024). "After treatment with cabergoline was started, PRL levels normalized, the visual deficit improved, and there was a slight adenoma reduction." (PMID 39051300, 2024). "Tumor #1 was composed of 90% adenoma tissue; it was densely granulated, stained positively for prolactin and synaptophysin and negatively for other adenohypophyseal hormones, and presented a proliferation index (MIB-1) < 1%." (PMID 39876960, 2024). "Histological findings: In MEN1, 66.7% of adenomas are both GH- and prolactin-positive in immunohistochemistry, compared to isolated acromegaly (76.1%)." (PMID 39194755, 2024). "We present a novel, multilevel Bayesian logistic regression approach to compute observationally constrained gender-specific prolactin thresholds in a large cohort of prolactinoma patients (N = 133) with respect to dichotomized adenoma size." (PMID 38544490, 2024). "Patient’s health stabilisation, normal level of prolactin and reduction in size of adenoma were achieved due to administration of combined treatment with tamoxifen and dopamine agonists." (PMID 38311996, 2024). "Dynamic studies in larger populations with treatment-naïve adenomas should be performed for more adequate analysis of the relationship between tyrosine uptake and prolactin levels." (PMID 39042164, 2024). "The patient was started on cabergoline with eventual normalization of the prolactin level and regression of the adenoma on follow-up imaging." (PMID 39050327, 2024). "Treatment with cabergoline (1.5 mg weekly) normalized prolactin concentrations and induced a major shrinkage of the adenoma." (PMID 38390203, 2024). "Dopamine agonists (DAs) are the first-line choice, with strong efficacy to achieve both serum prolactin (PRL) normalization and adenoma size reduction, even to the extent of definitive cure." (PMID 38544490, 2024). "Six months later, a follow-up brain MRI showed a 30% reduction in the size of the adenoma and there was a significant reduction in the prolactin level." (PMID 39221401, 2024). "The two populations analysed were comparable in terms of age at diagnosis, age at pregnancy, prevalence of macro/microadenoma, adenoma size at diagnosis and PRL levels at diagnosis." (PMID 38499816, 2024). "This study was consequently undertaken to explore the impact of chronic PRL elevation on cardiac morphology and function in human subjects with PRL-secreting adenoma." (PMID 36836192, 2023). "In the partial correlation analysis, controlling for age and weight, serum PRL levels exhibited a strong positive correlation with the maximum adenoma diameter (r=0.768, p<0.001)." (PMID 37664314, 2023). "Two individuals had co-secreting adenomas with one having immunohistochemistry showing positive staining for prolactin, growth hormone (GH), and adrenocorticotropic hormone (ACTH)." (PMID 36967793, 2023). "The most common type was ACTH-secreting adenoma (90/232), followed by prolactin-secreting adenoma (63/232), and growth hormone-secreting adenoma (41/232)." (PMID 38023185, 2023). "The BC rate varied substantially across the three periods due to the high percentage of macroadenomas (94.7%) and Knosp grade 3–4 adenomas (47.4%) among our PRL-secreting adenomas, which were known to impact the surgical cure rate." (PMID 37025271, 2023). "CAI at last follow-up was present in two out of the patients affected by micro (2.3%, one ACTH-secreting adenoma and one prolactin-secreting, both surgically resected) and in 15 with macro (19%), compared to 14 (51.9%) of Group B (χ2 = 10.9 p = 0.002)." (PMID 36001286, 2023).
adenoma (continued). "Atypical behavior of benign adenomas, including rapid growth, spontaneous normalization of prolactin, or progression despite medical treatment should prompt medical teams to reconsider their diagnosis." (PMID 36909111, 2023). "TAs had the highest rate of remission (N = 9, 90%), followed by CAs (N = 111, 77.6%), SAs (N = 60, 61.9%), LAs (N = 58, 60.4%), MSAs (N = 17, 56.7%), and mixed GH/PRL adenomas (N = 6, 37.5%)." (PMID 37717023, 2023). "A more conservative surgical strategy was utilized for PRL-secreting adenomas, particularly those invading the cavernous sinus, because surgery followed by an adjuvant dopamine agonist can effectively control most of these adenomas." (PMID 37025271, 2023). "It's interesting to note that as people age, certain strains of rats, in particular,typically acquires prolactin-secreting adenomas." (PMID 38250535, 2023). "Using double immunogold labeling in GH-PRL adenomas, they observed that most tumor cells contained dual hormone particles, and some cells contained only GH or PRL particles." (PMID 38260014, 2023). "Only GH and PRL co-secretion (MSA + mixed cell GH/PRL adenomas) subtypes were statistically significant in multivariate analysis and both displayed ORs < 1 (i.e., are negative predictors of postoperative disease remission)." (PMID 37717023, 2023). "Dopamine agonists (DA) are recommended as first-line therapy in prolactin-secreting adenomas leading to prolactin normalization and tumor shrinkage in the majority of the cases." (PMID 36928728, 2023). "Although there is a clear correlation between size of adenoma and PRL levels before and after treatment, there are cases of discordance between tumor changes and PRL levels during therapy." (PMID 35000899, 2022). "The postoperative follow-up was marked by the normalization of PRL, the disappearance of the adenoma, and the return of menstrual cycles." (PMID 36540468, 2022). "In that case, mutations in this receptor are expected to be related to the formation, progression, or prognosis of PRL-secreting adenomas." (PMID 36714572, 2022). "With regard to prolactin co-secreting adenomas, 13 showed high expression of SSTR2a, and only one had a low SSTR2a expression rate." (PMID 34674191, 2022). "At first diagnosis 3 patients had an ACTH-producing adenoma, 1 a prolactinoma and 1 a double secreting adenoma (GH and prolactin)." (PMID 36157469, 2022). "The SWIG-group consisted of seven non-functioning adenomas, four GH-secreting, two ACTH-secreting, one TSH-secreting, and 2 PRL-secreting adenomas." (PMID 35344185, 2022). "Baseline median prolactin level at presentation was 510 ng/ml (61-56670) and mean adenoma size was 2.18 cm (0.20-7.0)." (PMID 36337795, 2022). "Most MP patients in postmenopausal age show response to DA therapy with PRL level normalization and adenoma shrinkage." (PMID 35000899, 2022). "A diagnosis of prolactinoma is usually confirmed by serum prolactin levels >250 g/L combined with adenoma detection on high-resolution and postcontrast gradient echo (GRE) magnetic resonance (MR) imaging." (PMID 38983521, 2022). "Both hormonal and tumoral effects are mediated by the binding of DA to D2R on the membrane of adenoma cells, leading to reduction in synthesis and secretion of PRL and shrinkage of adenoma cells up to apoptosis." (PMID 35000899, 2022). "One-fourth of TSH PitNETs are plurihormonal adenomas of Pit-1 lineage with hypersecretion of other pituitary hormones, mainly growth hormone (GH) (18%) and prolactin (PRL) (9%)." (PMID 36539773, 2022). "Although histology was unable to confirm an adenoma (insufficient sample), immediately following surgery the patient’s serum prolactin was normal, and she remains in remission 2 years after surgery with no pituitary hormone deficits." (PMID 35608811, 2022).
adenoma (continued). "In conclusion, patients with prolactin-secreting adenomas have cognitive impairment, which has already been shown in previous research." (PMID 36581642, 2022). "Hypogonadism is often present at diagnosis of PRL-secreting adenoma as PRL regulates gonadal steroid secretion." (PMID 35000899, 2022). "Bromocriptine being cost-effective is still being widely used in our region and we found it inferior to cabergoline in prolactin normalization, adenoma shrinkage and improvement of symptoms." (PMID 36337795, 2022). "Our sample mostly consisted of men, possibly because male pituitary prolactin-secreting adenomas are mostly macroadenomas, and macroadenomas are often accompanied by cystic changes." (PMID 35741585, 2022). "Studies have suggested that the cystic part of pituitary prolactin-secreting adenomas lacks dopamine receptors compared to that in the solid part, contributing to the poor therapeutic effect and often resulting in the need for surgical intervention." (PMID 35741585, 2022). "Nonetheless, a persistent hyperprolactemia led to the initiation of fractionated radiotherapy (50Gy, 25 fractions of 2Gy) resulting in an involution of the remaining adenoma and a significant decrease of prolactin levels (422,48μg/L to 219,6μg/L)." (PMID 36157469, 2022). "Thirty patients with microprolactinomas had a normalization of prolactin level within an average of five months, and we saw a regression of the size of the adenoma in 43.2% of patients, stabilization in 24.3% and a progression of the process in 5.4% of cases." (PMID 36540468, 2022). "Of the 4 prolactinomas in the set, 1 showed continued adenoma growth and rising PRL levels despite cabergoline dose up to 7 mg/day, multiple surgeries, and RT." (PMID 34867776, 2021). "These two pathological subtypes considered single staining adenomas, approximately a quarter of somatotropic adenomas also prolactin (PRL)-positive, so-named dual staining (or mixed GH-PRL) adenomas." (PMID 34530798, 2021). "Postoperative pathological examination of the tumor revealed a plurihormonal adenoma that was secreting prolactin and follicle-stimulating hormone-β but with a very low number of Ki-67 positive cells (17 per three high-power fields)." (PMID 34039424, 2021). "Consistent with the findings by Hagiwara, we found that GH-producing adenomas had a lower T2 signal intensity ratio than PRL-producing adenomas and NF adenomas." (PMID 33881731, 2021). "In 5 patients with DA-resistant prolactinomas, treatment with octreotide LAR and cabergoline reduced PRL levels in 2 patients, with a 93% reduction in adenoma size; SST5 expression was noted in 1 responder." (PMID 34867776, 2021). "DAs yield an excellent therapeutic response in reducing tumor size and hormonal secretion targeting the dopamine receptor type 2 (D2DR) whose higher expression in prolactin-secreting adenomas compared to other PitNET is now well established." (PMID 35095761, 2021). "Six of these ten patients had prolactin-positive adenomas, and all of them experienced recurrence during follow-up." (PMID 35154007, 2021). "In men, PRLomas are almost ten times less frequent than in females and they are more frequently macro-adenomas, with higher PRL levels (> 1000 μg/L), aggressive behaviour and DA-resistance." (PMID 34173929, 2021). "The respective mean values of the WR, EER, and DER were 9.4%, 75.2%, and 64.5% for GH-producing adenomas; 6.2%, 117.1%, and 106.2% for PRL-producing adenomas; and 5.4%, 116.7%, and 108.7% for NF adenomas." (PMID 33881731, 2021). "Mammosomatotroph tumors look like DG adenomas in IHC method, but they also express estrogen receptor (ER) and prolactin." (PMID 34530798, 2021). "The respective mean values of WR, EER, and DER were 9.4%, 75.2%, and 64.5% for GH-producing adenomas; 6.2%, 117.1%, and 106.2% for PRL-producing adenomas; and 5.4%, 116.7%, and 108.7% for NF adenomas." (PMID 33881731, 2021).